CLDN1 (claudin 1)
Diseases named in the same sentence as CLDN1 in open-access papers (continued):
Sharing a sentence is not in itself a finding about the gene and the disease.
colon carcinoma (continued). "In addition, claudin-1 and claudin-2 were up-regulated in IBD-associated dysplasia and sporadic adenomas, as well as in colon carcinomas and metastatic lesions, suggesting their involvement in tumorigenesis and the invasiveness of colonic epithelial cells." (PMID 36826032, 2023). "We show that high CLDN1 expression in liver metastases of CRC patients was associated with a poor response to chemotherapy and that membrane expression of CLDN1 was induced by chemotherapy in colon cancer cell models." (PMID 37041570, 2023). "CLDN1 expression confers resistance to anoikis in colon cancer cells." (PMID 36672179, 2023). "CLDN1 overexpression, on the other hand, increased c-Myc levels in colon cancer cells." (PMID 36672179, 2023). "CLDN1 overexpression increased Notch and Wnt signaling at the transcriptomic level, as evidenced by an increase in Hes1 and a decrease in Math1 expression in a mouse colon cancer model." (PMID 36672179, 2023). "In addition, TSA inhibited colon cancer cells by altering claudin-1, a protein involved in the growth of colon cancer at high levels." (PMID 36297347, 2022). "E-cadherin expression was reduced by Claudin-1 via upregulating of ZEB-1 in colon cancer cells." (PMID 35280730, 2022). "Furthermore, TSA decreased the stability and suppressed the expression of claudin-1 mRNA by reducing the binding of HuR and increasing the binding of TTP to the 3′-UTR of claudin-1 in human colon cancer cell lines SW480 and SW620." (PMID 36297347, 2022). "Indeed, it has recently been shown that HDACs regulate the expression of Claudin-1 and Claudin-2 in colon cancer cells." (PMID 34830995, 2021). "A study has reported novel post-transcriptional regulation of claudin-1 in colon cancer cells, the authors documented the role of histone deacetylase (HDAC)-dependent histone acetylation as a key post-transcriptional regulation over claudin-1 expression, as found through HDAC inhibitor studies." (PMID 31861759, 2019). "Immunoblotting results showed that expression of CAM molecules, such as claudin-1, −3 and −4, EpCAM, E-cadherin, and Tspan8 were very low in normal colon cancer cell line CCD18Co compared to Caco-2, DLD-1 and SW620 colon cancer cell lines but no expression was observed in DLD-1 cells for Tspan8." (PMID 30289336, 2019). "Additionally, expression of Claudin-1 provided resistance to anoikis in gastric and colon cancer cells, as well as resistance to apoptosis in nasopharyngeal carcinoma cells." (PMID 31467400, 2019). "Similarly, others showed that elevated expression of EpCAM and altered expression of claudins, especially increases in the expression of claudin-1, −3, −4 and downregulation of claudin-7, are closely related to the metastasis process in colon cancer cells." (PMID 30289336, 2019). "Authors of this study reported that sodium butyrate and trichostatin A, two structurally different HDAC inhibitors, significantly inhibited the expression of TJ protein claudin-1 in colon cancer cells, seemingly through the modulation of claudin-1 mRNA stability." (PMID 27869761, 2016). "Claudin-1 has been reported to augment xenograft tumor growth and metastatic behavior in athymic mice through its effects on E-cadherin expression and β-catenin/Tcf signaling in colon carcinoma." (PMID 26083392, 2015). "β-catenin might partake in the process of CLDN1 regulated anoikis which had been mentioned in colon cancer." (PMID 25544763, 2015). "The dissent was that inhibition of CLDN1 in colon cancer cell induced a significant decrease only in MMP-9 activity, but not in MMP-2 activity, which suggested other mechanisms might be involved in the CLDN1 related invasion and metastasis." (PMID 25544763, 2015). "By contrast, we and others have shown that the claudin-1 expression is upregulated in human colon cancer and that modulation of claudin-1 expression positively regulates the tumor growth and metastasis in xenograft models using colon cancer cells." (PMID 24997475, 2014).
colon carcinoma (continued). "Additionally these findings provide further support of a potential role for inflammation in claudin-1-mediated colon cancer progression." (PMID 24997475, 2014). "Additionally, microarray and qPCR analyses of colonic tumors were performed to assess molecular changes due to claudin-1 expression." (PMID 24997475, 2014). "Recent studies have reported a controversial role for claudin-1 during colorectal carcinogenesis; increased claudin-1 expression was observed in hepatic metastatic lesions of colorectal cancer, but this expression was decreased in the lymph node metastases of colon carcinomas." (PMID 24069372, 2013). "For example, down-regulation of claudin-1 has been found in colon cancer." (PMID 24245968, 2013). "Knockdown of claudin-1 by siRNA resulted in the inhibition of migration in colonic cancer cells." (PMID 24073219, 2013). "Although long suspected to play an active role in tumorigenesis, only recently have a number of studies demonstrated that claudin 1 directly participates in the progression of several cancers including melanomas, oral squamous cell carcinomas and colon cancers." (PMID 23721519, 2013). "Importantly, further analysis demonstrated a significant correlation (p<0.01) between claudin-1 and Cdx2 expressions in 36∶50 (72%) colon cancer samples." (PMID 22719836, 2012). "Therefore, we investigated a possible correlation between Cdx2 and claudin-1 expressions in colon cancer." (PMID 22719836, 2012). "Claudin-1 expression positively correlates with tumor progression and metastasis in colon cancer." (PMID 22719836, 2012). "Also, in colon cancer patient samples, we observed a significant and parallel correlation between claudin-1 and Cdx2 expressions." (PMID 22719836, 2012). "Unexpectedly, overexpression of claudin 1 in a colon carcinoma line expressing low levels of this TJ protein and having epithelioid morphology resulted in the redistribution of E-cadherin from areas of cell-cell contact and epithelial-mesenchymal transition of these cells." (PMID 18162136, 2007). "Taken together, CLDN1 appears to have a complex role in colon cancer – it may facilitate early invasion and metastasis, but its absence in certain contexts (late-stage tumors) further exacerbates malignancy, possibly due to complete loss of junctional control and full EMT." (PMID 40687428, 2025). "We previously developed a monoclonal antibody (mAb) that targets the membrane form of claudin-1 (CLDN1) and showed that it could inhibit the growth of colon cancer cells expressing CLDN1, suggesting that CLDN1 targeting could be of clinical benefit for a subset of CRC patients." (PMID 37041570, 2023). "In line with this hypothesis, the nuclear localization of Cldn-1 was depicted in both colon cancer tissues and colon cancer-derived liver metastases, whereas Cldn-1 localization in normal human colonic mucosa is exclusively restricted to the basolateral membrane." (PMID 33584695, 2020). "Additionally, earlier studies have shown that claudin-1 downregulation was related to disease recurrence and poor patient survival in stage II colon cancer and that the decreased expression of this protein was also observed in lymph node metastases of colon carcinomas." (PMID 24069372, 2013). "Claudin-mediated signaling crosstalk with EMT pathways has been reported; for instance, CLDN1 can upregulate ZEB1 and repress E-cadherin in colon cancer cells to promote invasion." (PMID 40687428, 2025). "Smad4 is a central intracellular signal transduction component of the TGF-β family that was described to mediate invasion suppressive effects in colon cancer via the modulation of β-catenin/TCF-LEF activity, resulting in the repression of CLDN1 transcription." (PMID 36672179, 2023). "The KEGG analysis revealed correlations of AJUBA, CLDN1, and PHLPP2 with signaling pathways related to the occurrence and progression of colon cancer." (PMID 32633726, 2020).
colon carcinoma (continued). "Nuclear localization of claudin-1 induces structural and functional changes in EMT markers in colon cancer." (PMID 31717460, 2019). "In accordance with these studies, Notch-signaling was shown to be regulated by claudin-1 overexpression, which in turn increase the MMP-9 and p-ERK expression in transgenic mice resulting in metastasis of colon cancer and colonic epithelial homeostasis." (PMID 30728783, 2018). "To further assess global changes that occur as a result of claudin-1 upregulation, we performed transcriptome analysis of colonic tumors from APCMin and APC-Cldn1 mice to identify differentially expressed genes (DEGs)." (PMID 24997475, 2014). "Claudin-1 engages the downstream PI3K/AKT survival pathway, thus contributing to anoikis resistance in colon cancer." (PMID 24497940, 2014). "In colon cancer cells, caudal homeobox proteins (Cdx1 & Cdx2) and GATA4 in cooperation with the Wnt pathway are involved in claudin-1 promoter activation." (PMID 24009024, 2013). "Our further studies using full length and/or deletion mutant constructs in two different human colon cancer cell lines, SW480 and HCT116, showed key role of Cdx1, Cdx2 and GATA4 in the regulation of claudin-1 mRNA expression." (PMID 22719836, 2012). "We next stimulated OVCAR-3 and HT-29 colon cancer cells with 10 μM LPA for various times and examined effects on claudin-1 localization." (PMID 19440550, 2009). "A recently published study reported that ADCs targeting the tight junction protein claudin-1 (CLDN1) could be relevant to circumvent acquired resistance to chemotherapy and improve outcome in patients with advanced colon cancer." (PMID 39065798, 2024). "Additionally, CLDN1 can upregulate ZEB-1, which reduces E-cadherin expression in colon cancer cells, increases their invasive activity and decreases anoikis." (PMID 36620607, 2022). "We have previously demonstrated that claudin-1 mediates its pro-carcinogenic and metastatic effects through the activation of Src and Akt signaling, and claudin-7 regulates ERK signaling to modulate EMT in colon cancer." (PMID 34571860, 2021). "To test whether PIK3CA, SLC6A6, TMEM-43, and ASAP-1 expression is driven by CLDN1 and CLDN7 expression, we analyzed these genes and proteins in CLDN1-overexpressing SW480 (SW480CLDN1) and CLDN7-knockdown DLD-1 (DLDCLDN7KD) colon cancer cell lines." (PMID 34571860, 2021). "HT-29 cells were used as a model for comparison to OVCAR-3 because claudin-1 is a regulator of metastasis in colon cancer and not all cell types express claudin-1." (PMID 19440550, 2009). "CLDN-1 might enhance Zeb-1 levels through phosphatidylinositol-3 kinase (PI3K)/protein kinase B (Akt) pathway and Wnt/β-catenin pathway to suppress E-cadherin-related EMT pathogenesis in colon cancer." (PMID 33407452, 2021). "However, even though claudin-1 is upregulated in human colon cancer tissues when compared with adjacent normal epithelia, claudin-1 reduction is strongly correlated with poor prognosis, including high recurrence rate and poor survival, in tumor-node-metastasis (TNM) stage II colon cancer patients." (PMID 31316506, 2019).
colorectal cancer (61 papers, 2005 to 2026). A primary or metastatic malignant neoplasm that affects the colon or rectum. "Previous studies showed that claudin-1 overexpression is associated with the malignant behavior of colorectal cancer." (PMID 35280730, 2022). "In two studies on colorectal cancer, low expression of CLDN1 was a predictor of poor prognosis, however an association between high CLDN1 expression and depth of tumor invasion was also noted." (PMID 24321518, 2013). "Expression of the four-exon CLDN1 gene, formerly named senescence associated epithelial membrane protein, was identified in testis, colorectal carcinoma and lung." (PMID 15743508, 2005). "Moreover, the depletion of RBM47 led to the downregulation of epithelial-associated genes including OCLN, CDH1, TJP1, and CLDN1 with a concomitant enhancement in cell migration, mesenchymal markers, invasion and metastasis in colorectal cancer, which was consistent with our report." (PMID 35831298, 2022). "In contrast, HT-29 cells, originating from colorectal cancer, exhibit higher basal autophagy and altered claudin-1 expression compared with normal cells, making them more appropriate for mechanistic exploration under tumor-associated pathological conditions." (PMID 41211066, 2025). "CLDN1 is dysregulated in multiple cancer types, including colorectal cancer (CRC), where it is overexpressed in primary tumors and CRC metastases." (PMID 38371623, 2024). "Based on the currently available body of work on the protein expression of claudins in colorectal cancer, CLDN1, CLDN2, CLDN4, and CLDN18 have all been reported to be expressed in CRC." (PMID 38540693, 2024). "CLDN1 regulates intercellular adhesion in various cell types, including cervical adenocarcinoma, colorectal cancer, and triple-negative breast cancer." (PMID 39457456, 2024). "Claudin-1 (CLDN1) promotes colorectal cancer (CRC) cells’ chemoresistance by interacting with and stabilizing EphA2." (PMID 38391938, 2024). "Using patient samples, it has been shown that chemotherapy resistance is significantly correlated with elevated CLDN1 expression and that CLDN1 mRNA levels were upregulated in primary colorectal cancer tumors and metastases following chemotherapy." (PMID 38371623, 2024). "In another experimental system of colorectal cancer cells expressing BRAF with V600E mutations, inhibition of the mutant BRAF by small kinase inhibitors upregulated claudin 1, which was suppressed in cells with constitutively active mutant BRAF." (PMID 37998722, 2023). "A precedent of this dual role for claudin-1 seen above in TNBC patients was also reported recently in colorectal cancer patients." (PMID 37102018, 2023). "Efforts to translate the findings of claudin pathophysiology in clinical colorectal cancer have started with the generation of murine monoclonal antibodies against claudin 1 and the discovery of claudin inhibitors." (PMID 37998722, 2023). "A monoclonal antibody blocking claudin 1 was successful in reducing proliferation and survival of colorectal cancer cells in vitro and xenografts in mice in vivo." (PMID 37998722, 2023). "A recent study, however, demonstrated that Lactobacillus-derived metabolites enhance the antitumor activity of 5-FU and inhibit metastatic behavior in 5-FU-resistant colorectal cancer cells by regulating claudin-1 expression." (PMID 36341441, 2022). "In human colorectal carcinoma, there is a significant increase of claudin-1, -3, and -4 expressions as compared with normal mucosa." (PMID 35736905, 2022). "A review of literature on the expression of claudin-1 in the development of colorectal cancer shows multidirectional changes in its expression." (PMID 34638619, 2021). "Recently, it was reported that tRF-20-M0NK5Y93 inhibited the EMT of colorectal cancer cells by targeting Claudin-1, thereby regulating the migration and invasion of colorectal cancer cells." (PMID 34537813, 2021).
colorectal cancer (continued). "Conversely, overexpression of claudin-1 increases cell invasion in oral squamous cell carcinoma, melanoma, colon, and colorectal cancers." (PMID 32309226, 2020). "Several studies showed a relationship between claudin-1 and colorectal cancer (CRC), but its prognostic significance is inconsistent." (PMID 32855635, 2020). "The over expression of CLDN1 has been reported to increase cell invasion in colorectal cancer and oral squamous cell carcinoma (OSCC)." (PMID 30910845, 2019). "For instance, previous work has shown that CLDN1 plays a key role in inflammation-induced growth and progression in patients with colorectal carcinoma." (PMID 30219077, 2018). "Specifically, Claudin-1 has been suggested to be involved in the regulation of colorectal cancer progression by up-regulating Notch- and Wnt-signaling and mucosal inflammation." (PMID 29284484, 2017). "This study identifies an essential role of claudin-1 protein in the regulation of colorectal cancer by upregulating Notch- and Wnt-signaling and mucosal inflammation." (PMID 24997475, 2014). "Taken together, our current studies provide a clear insight into the role of claudin-1 protein in the regulation of colorectal cancer potentially by upregulating the Notch- and Wnt-signaling and mucosal inflammation." (PMID 24997475, 2014). "The tight junction protein Claudin-1, a claudin family member, has been implicated in several gastro-intestinal pathologies including inflammatory bowel disease (IBD) and colorectal cancer (CRC)." (PMID 24997475, 2014). "Further, studies including ours have demonstrated that claudin-1 expression is dysregulated in a variety of cancers including colorectal cancer." (PMID 22719836, 2012). "Taken together, these data suggest a direct correlation between the expressions of Cdx2 and claudin-1 in colorectal carcinomas." (PMID 22719836, 2012). "Claudin 1 is normally expressed in different kinds of epithelial tissue and has been found to be upregulated in colorectal carcinoma it has also been suggested as a target of the Beta-catenin/Tcf signaling." (PMID 23675182, 2010). "An earlier study showed that Claudin-1 could attenuate E-cadherin expression in colorectal cancer by upregulating ZEB-1, which, in turn, promoted EMT and reduced anoikis." (PMID 37350934, 2023). "Moreover, claudin 1 was upregulated in colorectal cancer cells and in tumors in vitro and in vivo following oxaliplatin treatment and development of resistance." (PMID 37998722, 2023). "For instance, it has been shown that a new marker for colorectal cancer is the expression of CLDN1." (PMID 37799140, 2023). "However, in colorectal cancer, CLDN1 often becomes upregulated following chemotherapies, and overexpression of CLDN1 confers cells’ resistance to oxaliplatin." (PMID 38137355, 2023). "Recent research has also demonstrated that the traditional Chinese medication Antrodia camphorta (AC) inhibits the epithelial-mesenchymal transition (EMT) phenomena in vitro in human colorectal cancer cells via modifying the Wnt/-catenin and claudin-1 signaling pathways." (PMID 37799140, 2023). "Upregulation of CLDN1 expression was observed in patients with colorectal cancer, which could be a possible biomarker for colorectal cancer treatment." (PMID 36991484, 2023). "In addition, studies have shown that CLDN1 played an important oncogene in many cancers, such as esophageal squamous carcinoma, hepatocellular carcinoma and colorectal cancer." (PMID 34116704, 2021). "CLDN1 up-regulates invasive activity in the colorectal cancer cells." (PMID 32824620, 2020). "In a very recent study, CLDN-1 was successfully targeted with anti-CLDN1 near-infrared fluorophore to track the colorectal cancer cells, and it may provide a novel way for fluorescence-guided surgery of tumor." (PMID 31952355, 2020). "Increased CLDN1 protein level was related to metastasis capacity of colorectal cancer." (PMID 25544763, 2015).